ENSG00000286098 (novel protein)
Gene: Protein-coding gene on chromosome 19 (11,987,641 to 12,078,106, forward strand). Ensembl gene ENSG00000286098.
Genetic constraint (gnomAD): Loss-of-function variants: 3 observed, 2.44 expected, observed/expected ratio (o/e) 1.23, 90% interval 0.5 to 1.9. That is too few expected variants to judge how well the gene tolerates losing a copy. Missense variants: 747 observed, 748.14 expected, observed/expected ratio (o/e) 1, 90% interval 0.94 to 1.06. Synonymous variants: 237 observed, 240.65 expected, observed/expected ratio (o/e) 0.98, 90% interval 0.88 to 1.1.